RNU6-1151P (RNA, U6 small nuclear 1151, pseudogene)
Gene: Small nuclear RNA gene on chromosome 8 (9,287,472 to 9,287,578, reverse strand). Ensembl gene ENSG00000207415.
Homologues: Orthologues: macaque U6 (95% identical), chimpanzee U6 (93% identical), pig U6 (81% identical), guinea pig U6 (80% identical). Paralogues in human: RNU6-1060P (88% identical), RNU6-43P (88% identical), RNU6-543P (88% identical), RNU6-1243P (87% identical), RNU6-24P (87% identical), RNU6-41P (87% identical), RNU6-44P (87% identical), RNU6-116P (86% identical), RNU6-11P (86% identical), RNU6-1327P (86% identical), RNU6-1331P (86% identical), RNU6-15P (86% identical), and 1289 more.